OTUD6A (OTU deubiquitinase 6A)
Description:
Deubiquitinating enzyme that hydrolyzes 'Lys-27'-, 'Lys-29'- and 'Lys-33'-linked polyubiquitin chains. Also able to hydrolyze 'Lys-11'-linked ubiquitin chains.
Synonyms: DUBA2; FLJ25831; HSHIN6
Tractability: No criterion of Open Targets' tractability assessment is met for any kind of drug.
Target class: Enzyme; Hydrolase
Gene: Protein-coding gene on chromosome X (70,062,457 to 70,064,179, forward strand). Ensembl gene ENSG00000189401.
Subcellular location (Human Protein Atlas): Cytosol; Vesicles
Gene Ontology:
Molecular function: cysteine-type deubiquitinase activity; protein binding
Biological process: protein K11-linked deubiquitination; protein K27-linked deubiquitination; protein K29-linked deubiquitination; protein K33-linked deubiquitination; protein deubiquitination
Homologues: Orthologues: chimpanzee OTUD6A (97% identical), macaque OTUD6A (92% identical), pig OTUD6A (70% identical), dog OTUD6A (69% identical), mouse Otud6a (63% identical), rat Otud6a (63% identical), rabbit OTUD6A (56% identical), Drosophila melanogaster CG7857 (37% identical), Caenorhabditis elegans otub-3 (28% identical), zebrafish otud4 (11% identical), Drosophila melanogaster CG3251 (9% identical), Drosophila melanogaster otu (9% identical). Paralogues in human: OTUD6B (55% identical), OTUD1 (19% identical), OTUD5 (17% identical), OTUD3 (16% identical), OTUD4 (12% identical).